CD40 (CD40 molecule)
Diseases named in the same sentence as CD40 in open-access papers (continued):
Sharing a sentence is not in itself a finding about the gene and the disease.
melanoma (continued). "Two phase 2 studies are evaluating the activity of APX005M administered at two different schedules in patients with unresectable melanoma (NCT04337931) and an ongoing trial is evaluating neoadjuvant therapy with or without CD40 agonistic APX005M for locally advanced rectal carcinoma (NCT04130854)." (PMID 33804039, 2021). "In the B16.F10 melanoma model, endothelial expression of ICAM-1 and VCAM-1 was not changed after treatment with agonistic CD40-antibody or sunitinib alone, but combining these treatments led to a synergistic increase in ICAM-1 (p=0.043) and VCAM-1 (p=0.017) surface expression." (PMID 27385210, 2016).
atherosclerosis (106 papers, 1998 to 2025). A disease characterized by the build-up of fatty material and calcium deposition in the arterial wall resulting in partial or complete occlusion of the arterial lumen. "Collectively, in this report, we demonstrate a new mechanism underlying the contribution of PCBP2/rs1333046 to atherosclerosis‐associated cellular senescence by modulating the p16INK4a and CD40‐mediated SASP gene expression." (PMID 41216990, 2025). "Genetic analyses reveal that CD40 polymorphisms (rs1535045, rs4810485, rs4239702[C]-rs1535045[T], and rs1883832 C allele) are associated with increased overall atherosclerosis risk." (PMID 41268556, 2025). "Macrophage-specific CD40 deficiency (CD40mac -/-) limits atherosclerosis and systemic inflammation by suppressing pro-inflammatory macrophage polarization." (PMID 41268556, 2025). "CD40 is also associated with the development of diabetic kidney disease, atherosclerosis, and potentially, peripheral neuropathy." (PMID 38474393, 2024). "CD40 is expressed at low levels on monocytes and its upregulation is associated to inflammatory conditions such as atherosclerosis, multiple sclerosis and tuberculosis." (PMID 39159266, 2024). "In our previous research, we have shown that whole body deficiency of CD40, as well as cell-specific deficiency of CD40 in dendritic cells, adipocytes and macrophages, reduces atherosclerosis and especially plaque inflammation." (PMID 37215541, 2023). "In a murine atherosclerosis model, CD40 deficient mice had lower MPA and platelet-mediated leukocyte-endothelium interactions resulting in decreased plaque formation." (PMID 37255704, 2023). "The main driver of pro-inflammatory CD40 signaling seems to be leukocyte-dependent since impaired macrophage migration and decreased atherosclerosis was observed in leukocyte specific CD40-deficient mice." (PMID 36267276, 2022). "CD40 has been implicated in various disorders, such as atherosclerosis, cardiovascular, metabolic (arterial hypertension, diabetes mellitus, etc.), and the others." (PMID 34492072, 2021). "For further analysis of the CD40L-CD40 T cell—DC axis in atherosclerosis, we also generated mice deficient for CD40 in CD11c+ DCs (referred to as Cd40fl/fl/Cd11cCretg), which were backcrossed to Apoe−/− mice." (PMID 34145241, 2021). "The CD40(L)-IFN-γ association was also present in human atherosclerosis, as both sCD40L and sCD40 levels in plaque and plasma showed a significant correlation with plaque and plasma levels of IFN-γ." (PMID 34145241, 2021). "Cluster of differentiation 40 (CD40) is a well-known protein receptor that can recruit tumor necrosis factor receptor-associated factors (TRAFs) to drive atherosclerosis." (PMID 31984429, 2020). "Failure to promote atherosclerosis in MHCII- or CD40-deficient B2 transfer indicates that B2 cells promote atherosclerosis by activating Th1 cells and augmenting Th1 responses." (PMID 31998318, 2019). "In apoE‐deficient mice, deletion of CD40 or CD40L leads to attenuation of atherosclerosis, increasing ECM and preferential polarization towards the anti‐inflammatory M2 phenotype 113." (PMID 29364567, 2018). "CD40 signaling events have been linked to atherosclerosis and thrombosis, processes which are thought to develop in part due to persistent inflammation." (PMID 28801616, 2017). "We showed that a deficiency of hematopoietic CD40 decreased atherosclerosis and induced plaque stabilization in CD40 knock-out mice." (PMID 27146510, 2016). "Another top ranked SNP rs1883832 (CD40) is found to be associated with atherosclerosis in Chinese population." (PMID 25786114, 2015).
atherosclerosis (continued). "Our meta-analysis suggests that C allele rs1883832 in CD40 gene is positively associated with susceptibility to atherosclerosis, CAD and ACS whereas C allele appears to contribute to a decreased risk of IS in Chinese population." (PMID 24828072, 2014). "Further efforts for fine-mapping of CD40 gene region and functional analysis are required to identify causal variants and elucidate detailed mechanisms of CD40 polymorphisms in atherosclerosis." (PMID 24828072, 2014). "Either CD40 or CD40L deficiency in ApoE-/- mice abrogated atherosclerosis by increasing the extracellular matrix and promoting M2 macrophage polarization." (PMID 24398220, 2014). "In the current meta-analysis, pooling the data from 7 published case-control studies indicated a significant association between a single nucleotide polymorphism (SNP) rs1883832 in CD40 gene and atherosclerosis under dominant model in Chinese population." (PMID 24828072, 2014). "It has been demonstrated that CD40 and ApoE double deficient mice develop reduced levels of atherosclerosis when given a normal chow diet compared with control animals." (PMID 24478772, 2014). "Whereas disruption of sCD40L/CD40 has been shown to inhibit atherosclerosis and neointima formation after vascular injury, the underlying mechanisms have not yet been completely clarified." (PMID 23785403, 2013). "CD40 can also play a pathogenic role in atherosclerosis onset." (PMID 41294355, 2025). "Additionally, CD40-deficiency in CD11c+ DCs leads to decreased atherosclerosis, accompanied by a reduction in plaque T cells and a systemic reduction in Tregs." (PMID 39926714, 2024). "CD40 deficiency is associated with the promotion of structural features that are characteristic of a stable plaque phenotype, as well as a decrease in leukocyte adhesion to inflammatory cell migration and consecutive plaque formation in atherosclerosis." (PMID 38579073, 2024). "Although HSP70 has been implicated in the pathophysiology of atherosclerosis, it is currently unknown whether this includes interaction with CD40." (PMID 32222950, 2021). "In addition, CD40-CD40L interactions of platelets and neutrophils and other leukocyte subsets exacerbates atherosclerosis, while CD40 deficiency was associated with reduced atheroprogression." (PMID 35174225, 2021). "It is worth noting that recently Kosacka and colleagues found that OSA patients with increased UA concentration have a higher risk of atherosclerosis, as indicated by a higher level of soluble proatherogenic ligand CD40, and a higher prevalence of cardiovascular adverse events." (PMID 28831208, 2017). "In addition, miR-146a-5p targets TRAF6 and IRAK1, proteins that are part of the CD40 signaling pathway; CD40, which serves an important role in cellular communication during inflammatory responses, is implicated in atherosclerosis." (PMID 26956024, 2016). "Necrotic cells, which hallmark advanced atherosclerosis, may well fail to induce sufficient CD40 expression on DCs, which is an essential step to subsequent CD8+ Tcell activation." (PMID 26486587, 2015). "CD40L and its receptor, CD40, have been implicated in the pathogenesis of atherosclerosis." (PMID 19865524, 2009). "Moreover, CD40 has also been linked to the development of atherosclerosis." (PMID 41216990, 2025).
atherosclerosis (continued). "CD40 ligation induces a series of inflammatory and apoptotic mediators; hence, CD40 signaling has been associated with the pathophysiology of immunodeficiency, neurodegenerative disorders, collagen-induced arthritis, graft-versus-host disease, atherosclerosis, and cancer." (PMID 35955688, 2022). "In this manuscript, we have combined a murine monoclonal antibody against CD40 (a costimulatory molecule directly linked to plaque progression and present on many cells within the lesion) with Zirconium-89 to test its applicability to detect lesions in a mouse model of atherosclerosis using PET/CT." (PMID 35336782, 2022). "Furthermore, soluble CD40L levels have been positively correlated with obesity and metabolic syndrome, and studies in rodents have shown that vascular inflammation and atherosclerosis could be prevented by CD40 deficiency." (PMID 30089130, 2018). "Interestingly, fatty liver status shared several pathways also associated with atherosclerosis or atherothrombosis (CD40/CD40L signaling pathway, Netrin-1 signaling and pathways contributing to thrombosis) i.e., another lipid related condition where lipids are accumulated to artery wall." (PMID 29985430, 2018). "Also, the CD40 rs1535045 gene variant may influence development of subclinical atherosclerosis in RA patients." (PMID 23166616, 2012). "We consider CD40-expressing adipocytes to be more involved in the progression of atherosclerosis and obesity than in the development of arterial hypertension." (PMID 39899926, 2025). "Recently, it was shown that mice with a myeloid-specific CD40 knockout on an ApoE−/− background developed a less activated immune cell profile, reduced atherosclerosis, and increased alternative macrophage activation." (PMID 39899926, 2025). "Overexpressing CD40 on low-grade inflammatory monocytes is a critical contributor to the pathogenesis of atherosclerosis." (PMID 38579073, 2024). "Inhibition of CD40 or its ligand CD40L reduces the extent of atherosclerosis and induces plaque stability in hyperlipidemic mice by reducing major inflammatory pathways." (PMID 38554187, 2024). "A Cava rosé wine, with a medium-level polyphenol content, has been shown to reduce the inflammatory markers of atherosclerosis (adhesion molecules, cytokines, and the CD40/CD40L system) to a greater extent than other alcoholic beverages without polyphenols." (PMID 37111141, 2023). "Evidence suggests that TRAF6, a downstream target of CD40, is critical in the progression of atherogenesis, neointima development, and atherosclerosis when CD40 on macrophages is activated." (PMID 38084332, 2023). "CD40 is expressed by different kinds of cell types relevant to atherosclerosis, including endothelial cells, smooth muscle cells, macrophages, and lymphocytes." (PMID 35955688, 2022). "In CD40−/− ApoE−/− mice that lack CD40 as well as the ApoE receptor, thus suffering from a severely impaired capability to handle cholesterol, reduced atherosclerosis progression was observed in comparison to control mice when subjected to a high-fat diet." (PMID 36267276, 2022). "Blocking CD40/CD40L signaling by monoclonal antibodies was shown to be beneficial in the treatment of arthritis and atherosclerosis by disrupting CD40 function, and CD40 has been a key immunotherapeutic target for over 20 years." (PMID 35955688, 2022). "We show that this Zirconium-89 labeled antibody can detect CD40 in atherosclerotic lesions in a mouse model of atherosclerosis." (PMID 35336782, 2022). "The authors highlight the importance of procoagulant platelets in ischemic stroke and discuss P-selectin and CD40 involvement in atherosclerosis and platelet–neutrophil interplay in thrombus formation." (PMID 35409226, 2022).
atherosclerosis (continued). "We evaluated the uptake of [89Zr]Zr-anti-CD40 mAb in the ApoE−/− atherosclerosis mouse model using PET imaging." (PMID 35336782, 2022). "On the other hand, in human monocytes and monocyte-derived dendritic cells, the upregulation of α7-nAChRs and M1 marker CD40/CD86 enhances adaptive immunity in atherosclerosis, including T cell proliferation and cytokine production." (PMID 35096275, 2022). "Platelet CD40 has also been shown to promote atherosclerosis by stimulating leukocyte and endothelial cell activation." (PMID 34360659, 2021). "Previous studies showed that inhibition of the co-stimulatory CD40 ligand (CD40L)-CD40 signaling axis profoundly attenuates atherosclerosis." (PMID 34145241, 2021). "During the development of atherosclerosis, CD40 and CD40L are expressed on the majority of immune cells in the circulation and immune cells and non-immune cells within the atherosclerotic plaque." (PMID 32222950, 2021). "As atherosclerosis is also present in the coronary arteries, and plaque rupture can lead to myocardial infarction, the CD40/CD40L dyad is intimately involved in the pathophysiology of the underlying disease." (PMID 33198327, 2020). "CD40 is different from CD40L, and the role of the receptor CD40 in the development of atherosclerosis remains disputable." (PMID 33371312, 2020). "The adoptive transfer of Tregs ameliorated atherosclerosis via CD40/CD40L interaction, whereas depletion of Tregs exacerbated the vascular inflammation with disturbed lipid phenotype, confirming an atheroprotective role for Tregs." (PMID 32849502, 2020). "The TRAFs known to elicit CD40 signaling appear to show fundamental differences regarding their involvement in atherosclerosis and metabolic disorders." (PMID 33198327, 2020). "We found compelling evidence that B cells interact with CD4 T cells using MHCII and CD40 molecules to increase atherosclerosis development." (PMID 31998318, 2019). "Our study demonstrates that interaction between B and CD4 T cells utilizing MHCII and CD40 is essential to augment their function to increase atherosclerosis in hyperlipidemic mice." (PMID 31998318, 2019). "We have previously reported that siRNA-silencing of CD40 (siCD40) reduced atherosclerosis (ATH) progression." (PMID 31889910, 2019). "Genetic and antibody-mediated inhibition of CD40 or CD40L successfully reduced disease burden in experimental models of atherosclerosis, Crohn’s disease, psoriasis, rheumatoid arthritis (RA), and experimental autoimmune encephalomyelitis (EAE)." (PMID 29312317, 2017). "The CD40:CD40L two-way immune checkpoint promotes atherosclerosis and inhibits tumor progress and has been used as a cancer immunotherapy target." (PMID 28738836, 2017). "CD40:TRAF6 has a critical role in promoting atherosclerosis, as attenuated atherosclerosis and reduced Ly6C+ MC and M1 MØ were observed in CD40−/−TRAF6−/−ApoE−/− but not in CD40−/−TRAF2/3/5−/−ApoE−/− mice." (PMID 28738836, 2017). "In the data presented about atherosclerosis, interfering with CD40 macrophage signaling induces a phenotype shift from M1 to M2 macrophages." (PMID 27146510, 2016). "In the pathophysiology of coronary artery disease, macrophage-specific CD40 plays a role in four major processes of the disease, atherosclerosis, neointima formation, angiogenesis, and arteriogenesis." (PMID 27146510, 2016). "CD40, which is known to serve a critical role in the process of atherosclerosis was predicted as one of the targets." (PMID 27731400, 2016). "We provide the scientific community with a set of genes whose expression is increased during atherosclerosis progression but downregulated upon CD40 silencing." (PMID 27924297, 2016). "Our results extend recent reports describing a role of CD40 for interactions between platelets, endothelial cells, and leukocytes in atherosclerosis." (PMID 27152726, 2016).